ANAPC15 (anaphase promoting complex subunit 15)
Description:
Component of the anaphase promoting complex/cyclosome (APC/C), a cell cycle-regulated E3 ubiquitin ligase that controls progression through the cell cycle. APC/C acts by mediating ubiquitination and subsequent degradation of target proteins: it mainly mediates the formation of 'Lys-11'-linked polyubiquitin chains and, to a lower extent, the formation of 'Lys-48'- and 'Lys-63'-linked polyubiquitin chains. APC/C catalyzes assembly of branched 'Lys-11'-/'Lys-48'-linked branched ubiquitin chains on target proteins. APC/C is activated by CDC20 in the metaphase/anaphase transition of cell cycle, targeting the degradation of cyclin B and securin. APC/C is regulated by the mitotic checkpoint complex (MCC), which inhibits APC/C and delays chromosome segregation. Also required for degradation of CDC20.
Synonyms: APC15; C11orf51; HSPC020; DKFZP564M082
Tractability: No criterion of Open Targets' tractability assessment is met for any kind of drug.
Gene: Protein-coding gene on chromosome 11 (72,106,378 to 72,113,688, reverse strand). Ensembl gene ENSG00000110200.
Subcellular location (Human Protein Atlas): Nucleoplasm; Vesicles
Pathways (Reactome):
Cell Cycle: APC-Cdc20 mediated degradation of Nek2A; APC/C:Cdc20 mediated degradation of Cyclin B; APC/C:Cdc20 mediated degradation of Securin; APC/C:Cdc20 mediated degradation of mitotic proteins; APC/C:Cdh1 mediated degradation of Cdc20 and other APC/C:Cdh1 targeted proteins in late mitosis/early G1; Autodegradation of Cdh1 by Cdh1:APC/C; Cdc20:Phospho-APC/C mediated degradation of Cyclin A; Conversion from APC/C:Cdc20 to APC/C:Cdh1 in late anaphase; Inactivation of APC/C via direct inhibition of the APC/C complex; Phosphorylation of the APC/C; Regulation of APC/C activators between G1/S and early anaphase; Separation of Sister Chromatids
DNA Replication: Assembly of the pre-replicative complex; CDK-mediated phosphorylation and removal of Cdc6
Cellular responses to stimuli: Senescence-Associated Secretory Phenotype (SASP)
Disease: Aberrant regulation of mitotic exit in cancer due to RB1 defects
Gene expression (Transcription): Transcriptional Regulation by VENTX
Gene Ontology:
Molecular function: protein binding
Biological process: anaphase-promoting complex-dependent catabolic process; protein branched polyubiquitination; protein K11-linked ubiquitination; protein K48-linked ubiquitination; regulation of mitotic cell cycle spindle assembly checkpoint; regulation of meiotic cell cycle; regulation of mitotic cell cycle; protein ubiquitination
Cellular component: anaphase-promoting complex; cytosol; nucleoplasm
Genetic constraint (gnomAD): Loss-of-function variants: 10 observed, 18.06 expected, observed/expected ratio (o/e) 0.55, 90% interval 0.34 to 0.94. The upper end of that interval is the gene's LOEUF score, 0.94, which puts it in group 3 of 6, group 1 being the genes least tolerant of losing a copy. Missense variants: 85 observed, 155.05 expected, observed/expected ratio (o/e) 0.55, 90% interval 0.46 to 0.66. Synonymous variants: 45 observed, 51.89 expected, observed/expected ratio (o/e) 0.87, 90% interval 0.68 to 1.11.
Homologues: Orthologues: mouse Anapc15 (100% identical), pig ANAPC15 (98% identical), guinea pig ANAPC15 (96% identical), rat Anapc15 (90% identical), tropical clawed frog anapc15 (87% identical), dog ANAPC15 (86% identical), zebrafish anapc15 (80% identical).
Diseases named in the same sentence as ANAPC15 in open-access papers:
ANAPC15 is named in the same sentence as 2 diseases in open-access papers, as found by Europe PMC text mining. Sharing a sentence is not in itself a finding about the gene and the disease. The quoted sentences say what the papers report.
tumor (1 paper, 2019). "Several genes splicing events, including KIAA1715/56096/AP, ZNF567/49415/AP, NTMT1/87861/AP, ANAPC15/17570/AD, SRPK2/81284/ES, MTMR11/7413/AP, FNIP2/70999/AP, and TNC/87336/ES, differed significantly between tumor and normal samples." (PMID 31552163, 2019).
ANAPC15 also shares sentences with these, for which no sentence is quoted: glioma (1 paper).